IKBKB (inhibitor of nuclear factor kappa B kinase subunit beta)
Diseases named in the same sentence as IKBKB in open-access papers (continued):
Sharing a sentence is not in itself a finding about the gene and the disease.
myelosuppression (1 paper, 2017). Myelosuppression or bone marrow suppression is a condition in which bone marrow activity is decreased, resulting in fewer red blood cells, white blood cells, and platelets. "In some subgroups, cyclin D1 gene CCND1 rs9344 and inhibitor of κB kinase gene IKBKB rs12676482 were related with the grade 3–4 acute radiation-induced myelosuppression, and CCND1 rs9344 was also associated with grade 3–4 acute radiation-induced oral mucositis." (PMID 28445979, 2017).
myositis (1 paper, 2017). "First, NF-κB activation, which is a known regulator of skeletal muscle inflammation in myositis, occurs downstream of IKBKB, which transcribes the beta subunit (IKK-β) for the IKK enzyme complex." (PMID 28829792, 2017).
Nephropathy (1 paper, 2023). A nonspecific term referring to disease or damage of the kidneys. "In diabetic subjects, a downregulation of miRNA-199a was observed in nephropathy and the inhibitor of nuclear factor kappa b kinase subunit beta (IKKβ) was identified as a potential target." (PMID 37547923, 2023).
neuroendocrine prostate tumors (1 paper, 2017). "The analysis of the data included in cBioportal indicates that overexpression of IKBKB and copy-number amplifications are common, being IKBKB amplified at high level in around 25% of neuroendocrine prostate tumors." (PMID 29292732, 2017).
Nicotine addiction (1 paper, 2025). "Among these, the TGF-beta signaling pathway, T cell receptor signaling pathway, and Nicotine addiction pathway were highly enriched (p < 0.01) enriched involving relevant genes (PITX2, ID4, BMP4, DLG1, IKBKB, ICOS, GRIA3, and SLC17A6)." (PMID 40496916, 2025).
uterine corpus endometrial carcinoma (1 paper, 2023). A endometrial carcinoma (disease) that involves the body of uterus. "In addition, KRAS, IKBKB, and VCAN alteration frequencies across 32 human cancer types are tightly correlated, and were highest in LUAD, COAD/READ, and uterine corpus endometrial carcinoma (UCEC), cancers that commonly cause MPE." (PMID 36980752, 2023).
tumor (264 papers, 2006 to 2026). "Expression of inhibitor of nuclear factor kappa B kinase subunit beta (IKKβ)/NFκB has a tumor-suppressive function in CAFs in colitis-associated cancer." (PMID 37046676, 2023). "IKBKB/IKKβ, the core catalytic subunit of the κB kinase complex, is involved in mediating the classical NF-κB pathway, which plays an important role in tumor initiation by inducing DNA damage, oncogenic mutation and genomic instability." (PMID 34109216, 2021). "Furthermore, deficiency of circRNA-14,052 reduced xenograft tumor growth in vivo through targeting miR-214-3p/IKBKB/IL-6/JAK2/STAT3 axis." (PMID 41044672, 2025). "A relatively high number of mutations in IKBKB have been found in skin basal cell carcinomas, although the interpretation of these data is difficult due to the high mutation rate found in this particular tumor type." (PMID 29292732, 2017). "This suggests that the deficiency of miR-214-3p mediates the upregulation of IKBKB, which subsequently activates IL6/JAK/STAT3 signaling, thereby promoting tumor progression." (PMID 41044672, 2025). "NF-κβ transcription factor has been described to be involved in angiogenesis, and an inhibitor of nuclear factor kappa-B kinase subunit beta (IKKβ) has been shown to participate in the formation of tumor angiogenesis." (PMID 38999976, 2024). "A decrease in the levels of RELA, NOD1, CASP8, BCL2L1, ELK1, and IKBKB was identified in the poorly differentiated (G3) tumours compared with the moderately differentiated (G2) ones." (PMID 36433652, 2022). "In GBM, we observed IKBKB (down, alkaliptosis) as a target; it regulates alkaliptosis in tumor tissues." (PMID 33670487, 2021). "Excessive activity of IKBKB in oral and dental epithelial cells leads to changes in the composition of epithelial cells and the expression of several tumor suppressor proteins and miRNAs." (PMID 33552118, 2020). "The expression of FGFR3, PLCB4, and IKBKB were downregulated in the tumor tissues as compared to the adjacent normal tissues." (PMID 31729423, 2019). "Several members of the canonical NF-κB pathway were in the top list, including RELA, NFKB1, CHUK, IKBKB, IKBKG, and REL, indicating that the canonical NF-κB pathway was closely associated with immune-related DEGs in tumour serum-cultured DCs." (PMID 28350008, 2017). "In spite of this, in general, IKBKB is rarely mutated and COSMIC finds only five tumor types with mutations and always at low proportions." (PMID 29292732, 2017). "The significantly higher IKBKB expression was detected in tumor infiltrating CD11b+ cells isolated from low grade tumors than GBM." (PMID 26427514, 2015). "Through bioinformatics analysis, we screened potential target genes for miR-214-3p, and found that IKBKB may be the most likely target gene, which functions as tumor promoter in cancers." (PMID 41044672, 2025). "For example, one study showed that the expression level of IKBKB in KIRC is decreased, and the upregulation of IKBKB protein levels is associated with an increase in the tumor nuclei grade and a significantly shortened survival period, suggesting that the gene plays a carcinogenic role in KIRC." (PMID 37847185, 2023). "Similarly, hsa-miR-429 targets the inhibitor of nuclear factor Kappa B kinase subunit beta (IKKβ) and regulates NF-kB, suggesting its tumor-suppressive function." (PMID 36879084, 2023). "Moreover, a decrease in the levels of RELA, NOD1, CASP8, BCL2L1, ELK1, and IKBKB was identified in poorly differentiated tumours compared to moderately differentiated tumours." (PMID 36433652, 2022). "In addition, IKBKB has been shown to take part in tumor growth via NF-κB activation and the phosphorylation-dependent inhibition of tumor suppressors." (PMID 33041665, 2020). "IKBKB was observed in the areas of tumor ameloblasts that express keratin K5 at high levels." (PMID 33552118, 2020).
tumor (continued). "The results showed that the activation of IKBKA and IKBKB by CTGF could be specifically attenuated by the anti-TNFR1 antibody in the CTGF-high tumor cells." (PMID 26318291, 2015). "Studies have demonstrated that METTL3 enhances tumor cell proliferation and invasion through the MYC, inhibitor of nuclear factor kappa-B kinase subunit beta (IKBKB), and RELA proto-oncogene, NF-kB subunit (RELA) signaling pathways." (PMID 40678060, 2025). "Meanwhile, deficiency of circRNA-14,052 led to a significant decrease in circRNA-14,052, IKBKB, IL-6, JAK2, and STAT3 levels, and an increase in miR-214-3p levels in tumor tissues from MCF-7 tumor-bearing mice compared to the LV-NC group." (PMID 41044672, 2025). "Oxidative phosphorylation components (NDFs, COXs, TCIRG1, LHPP) and chemical carcinogenesis pathways involving reactive oxygen species (CYP1B1, GSTs, AKT2, IKBKB, MAPK3, MAP2K2) exacerbate DNA damage and promote tumour aggressiveness." (PMID 41007296, 2025). "When comparing the gene expression signature of poorly differentiated (G3) tumours with the moderately differentiated (G2) ones, the downregulation of RELA, NOD1, CASP8, BCL2L1, ELK1, and IKBKB was found." (PMID 36433652, 2022). "Thus, IKBKB was named after its function of phosphorylating I κB molecules, which is the inhibitor of NF-κB transcription factors, and indicates that IKBKB could act as a tumor suppressor." (PMID 30280037, 2018). "For spleens from tumor bearing old mice majority of the upstream regulators are either interferons (IFNγ, IFNα, IRF3, IRF7, and IFNA2) or are related to the immune system (IKBKB, CHUK, NFκB, NFκBIA, STAT3, and mir-21) and are predicted to be up-regulated." (PMID 26497558, 2015). "Thus, CHUK, IKBKB gene products, and co-chaperones FKBP5 (FKBP51), TSC1, and TSC2 interact with Hsp90 and behave like tumor suppressors, while AKT1 shows oncogenic behavior and is involved in the enhanced activity of many signaling pathways." (PMID 39337357, 2024). "Additionally, rosmarinic acid complements the action by targeting MAPK1, IKBKB, JUN, and RELA to synergistically inhibit the proliferation of tumor cells and induce apoptosis." (PMID 39840098, 2024). "In addition, CYCS and NFKB1 presented low expression, while IKBKB and TRADD presented high expression in TCGA and clinical tumor samples." (PMID 35502302, 2022). "hsa-miR-138-5p (up) regulating IKBKB in GBM, is reported to suppress tumor development in GBM." (PMID 33670487, 2021). "The activation of three stringent UPRs related to DNA damage pathways in both GL261 and LLC tumors (CHUK/IKBKA, IKBKB and JUN) or in all three tumor models (CHUK, IKBKB) may reflect the cytotoxic responses common to CPA treatment in all three tumor models." (PMID 27515027, 2016).
cancer (213 papers, 2009 to 2026). A tumor composed of atypical neoplastic, often pleomorphic cells that invade other tissues. "These investigations have also identified four potential EGCG target proteins linked to cancer development: IKBKB, KRAS, WEE1, and NTRK1." (PMID 38978121, 2024). "IKBKB has an important role in the NF-kappa beta signalling pathway, which is triggered by radiation and can cause resistance for irradiated cancer cells." (PMID 33382739, 2020). "In particular, changes in CHUK and IKBKB may be associated with the faster progression of these cancers." (PMID 39337357, 2024). "Interestingly, VCAN and IKBKB alterations (mostly missense mutations) each occur in 5% of all cancer patients and are significantly mutually enriched (VCAN in KRAS and IKBKB in VCAN mutations) suggesting mutual addiction." (PMID 36980752, 2023). "The upregulated DEPs associated with pathways in cancer were IKBKB, AGT, and PLCG2." (PMID 35334492, 2022). "In contrast, the IKBKB gene was upregulated in the subgroup of patients determined as N3 compared to N2 (p = 0.0363) for STAD cancer." (PMID 39337357, 2024). "In addition, the studied genes, especially CHUK and IKBKB, were upregulated in cancers with a higher degree of histological malignancy and a greater degree of lymph node infiltration, suggesting they may also be associated with cancer progression." (PMID 39337357, 2024). "In the COAD subgroup, the methylation status of the IKBKB gene promoter was significantly higher in cancer tissue than in healthy tissue (p < 0.001)." (PMID 39337357, 2024). "The IKBKB gene was an inhibitor of NF-kappaB transcription factors, while transcription factors of the NF-kappaB protein family were a key regulatory factor in immunity, inflammation, and cancer." (PMID 40496916, 2025). "In READ, only IKBKB gene expression was differentiated between cancer stages." (PMID 39337357, 2024). "Of the kinase inhibitor gene targets evaluated, high pre-treatment PIKFYVE, KDR, NTRK1, IKBKB, FLT1, or FGFR1 expression was each associated with lower odds of achieving CR when controlling for cancer type, biopsy site, age at the time of treatment initiation, and ICB agent." (PMID 38464258, 2024). "Moreover, networks related to “cancer” and “development disorders” were among the top enriched “Disease” networks while IL-1β, the NF-ĸB complex and IKBKB were among the most highly enriched “Upstream Regulators”." (PMID 32456215, 2020). "CovEx identified extra NCG cancer genes MECOM and NF1 and CGC cancer gene IKBKB." (PMID 28415609, 2017). "This may indicate the IKK complex, and especially the IKBKB gene, in the development of cancer." (PMID 39337357, 2024). "Moreover, among the enriched genes in the group of cancer areas in the dHGP, we detected many genes known to enhance inflammatory reactions in cancer by promoting the NFκB pathway (IKBKB, FKBP4), activating lymphocytes (TNFSF9, HLA-F) or recruiting neutrophils (DPEP1)." (PMID 36691028, 2023). "No other significant relationships were found regarding the connection between CHUK, IKBKB, or IKBKG gene expression and cancer type." (PMID 39337357, 2024). "For IKBKB, the results were the opposite; for example, in READ, its expression was higher in more advanced cancer, and in STAD, its expression was higher in the presence of lymph node metastases." (PMID 39337357, 2024). "IKBKB and IKBKG were both upregulated in all examined cancers, while CHUK only presented increased expression in ESCA and STAD." (PMID 39337357, 2024). "The correlation between CHUK, IKBKB, IKBKG, and the overall survival (OS) of patients with COAD, ESCA, READ, and STAD cancer was assessed using the KM plotter database." (PMID 39337357, 2024). "In the collected clinical specimens, qPCR results revealed notably lower CYCS and NFKB1 expression and notably higher IKBKB and TRADD expression in cancer tissues than in healthy paracarcinoma ones (P < 0.05)." (PMID 35502302, 2022).
cancer (continued). "Those events occurred on pre-mRNA of 56 genes including well-known cancer-related genes PTPRC, IKBKB and HRAS, and genes coding for transcription factors ILF2, ATF2 and EYA3." (PMID 34543356, 2021). "Our study lays the foundation for more comprehensive experimental study (in vitro, in vivo) on modulating the cell death drug targets FANCD2, NCOA4 (COAD), IKBKB, (GBM), and RHOA (GBM and SCLC), to improve the therapeutic avenues in cancer treatment." (PMID 33670487, 2021). "As such, changes in these genes may affect cancer development; however, the role of the CHUK, IKBKB, and IKBKG genes is not fully known." (PMID 39337357, 2024). "Since TRAF2, IKBKB, and TAB2 proteins are directly or indirectly involved in NFκB activation, the influence of these proteins on tumorigenesis is discussed in many studies related to cancer occurrence." (PMID 39061149, 2024). "We identified genes for which ASEs were observed in both the Afro-Caribbean cohort and the Jurkat cells expressing Tax or HBZ, including cancer genes EIF4A2, IKBKB, LZTR1, STAT6 (for Tax); CARS, MDM2, IKZF1 (for HBZ); and EWSR1, MUTYH, and PTPRC (for both Tax and HBZ)." (PMID 34543356, 2021). "Moreover, several mRNAs in the ceRNA network were enriched in pathways involved in cancer such as WNT11, FGFR3, PLCB4, and IKBKB." (PMID 31729423, 2019). "Interestingly, NEMO (IKBKγ) (FC 1.11), IKBKB (FC 0.94), NFκB1 (FC 0.92) and RELA (FC 1.12) were only slightly changed in carcinoma tissue compared to normal mucosa." (PMID 29188362, 2018). "Moreover, in addition to Lin28B there are several putative cancer stem cell markers, such as MUC1, CD38, FLOT2, EGF and IKBKB that were also upregulated (signal log2 ratio>0.5) in mH2A1-depleted LD611 cells." (PMID 26028027, 2016). "Subjecting quinoxaline analog libraries to both unbiased and biased screening strategies identified an orally bioavailable, non-ATP competitive inhibitor of nuclear factor kappa-B kinase subunit beta (IKKβ) inhibitor that exhibited anti-cancer effects in mouse models." (PMID 40363807, 2025). "It is worth noting that IKBKB, APOB and MAPK9 are not only vital cholesterol metabolism regulation genes but are also often upregulated in cancer, which implies that the use of cholesterol-lowering drugs in HNSCC patients with the overexpression of these genes may be helpful." (PMID 37568192, 2023). "Generally, the MEXPRESS database identified a weak negative correlation between the mRNA expression of CHUK, IKBKB, and IKBKG genes and the methylation status of particular CpG islands/dinucleotides in the investigated cancers." (PMID 39337357, 2024). "GEPIA analysis indicated lower expression of the IKBKB and IKBKG genes in all examined GI cancers compared to normal cells; however, in most cancers, the difference was not statistically significant." (PMID 39337357, 2024).
infection (74 papers, 2010 to 2025). The state of being infected such as from the introduction of a foreign agent such as serum, vaccine, antigenic substance or organism. "IKBKB and NF-kB signaling further recruit T-cells to the site of infection, where antigen presentation to CD4+ T-cells can lead to IFN-gamma expression, which has been identified as vital in the host response to intracellular bacteria." (PMID 39062990, 2024). "Similarly, IKBKB is related to inflammation and infection, and a persistent inflammatory response is a potential cause of tumors." (PMID 33614490, 2020). "On the contrary, inhibitory genes of NF-kappaB activity, e.g. IKBKB, NFKBIB and IKBKG decreased over infection time." (PMID 36544767, 2022). "The genes IKBKB, IRAK3, IRF5, MAP2K4 (MEK4), MAPK14 (p38), MAPK8 (JNK1) and NFKB1 (p50) were upregulated not only in both cell types, but also after infection with whole bacteria of P. gingivalis W83 as well as with the membrane fraction." (PMID 28056810, 2017).
metabolic disease (8 papers, 2012 to 2023). A congenital disorder (due to inherited enzyme abnormality) or acquired (due to failure of a metabolically important organ) disorder resulting from an abnormal metabolic process. "Equally, IKBKB encodes serine kinases and inhibits NF-κB signaling, which plays a key role in the inflammatory response, immune cell proliferation, and metabolic diseases." (PMID 38203330, 2023).
respiratory diseases (1 paper, 2024). "Next, complementary analyses identified nine DMGs (LTA, STAT3, IKBKG, IRAK1, NOD2, TLR2, TNFRSF1A, and IKBKB) that might be involved in the immune response of XJB cattle infected with respiratory diseases." (PMID 38732144, 2024).
IKBKB also shares sentences with these, for which no sentence is quoted: lung cancer (30 papers); prostate carcinoma (23); hepatocellular carcinoma (19); Hepatic steatosis (16); Hyperglycemia (16); overnutrition (16); Glucose intolerance (15); Arthritis (14); cervical carcinoma (13); multiple myeloma (13); bacterial infection (12); liver fibrosis (11); metabolic syndrome (10); inflammation (9); endothelial dysfunction (8); head and neck squamous cell carcinoma (8); Hypertension (8); non-small cell lung carcinoma (8); autoimmune disease (7); leukemia (6); ovarian tumor (6); Autoimmunity (5); cardiac hypertrophy (5); Cerebral ischemia (5); Cognitive impairment (5); liver disease (5); neurodegenerative disease (5); atopic dermatitis (4); experimental autoimmune encephalomyelitis (4); fibrosis (4).
A further 199 diseases each share a sentence with IKBKB in 4 papers or fewer.